UQCRFS1P1 (ubiquinol-cytochrome c reductase, Rieske iron-sulfur polypeptide 1 pseudogene 1)
Synonyms: formerly UQCRFSL1
Gene: Processed pseudogene on chromosome 22 (39,875,289 to 39,876,108, forward strand). Ensembl gene ENSG00000226085.
Subcellular location: Membrane